ZNRF3 (zinc and ring finger 3)
Diseases named in the same sentence as ZNRF3 in open-access papers (continued):
Sharing a sentence is not in itself a finding about the gene and the disease.
cancer (continued). "At the ZNRF3 locus, 22q12.1, there was a high frequency of deletion events in MSS cancers (BRAF mutant/MSS: 16/33, 48.5%; BRAF wild type: 10/18, 55.6%)." (PMID 27661107, 2016). "Collectively, these results suggest that disruption of ZNRF3 and RNF43 may up-regulate EGFR protein levels in human cancers." (PMID 38260423, 2024). "However, the extent to which ZNRF3 and RNF43 act on other substrates, apart from WNT receptors, to influence development and cancer has been unclear." (PMID 38260423, 2024). "Understanding how ZNRF3/RNF43 regulates EGFR and the crosstalk between EGFR and WNT receptors may offer potential therapeutic targets for cancer treatment." (PMID 38260423, 2024). "Together, these data highlight ZNRF3 and RNF43 as novel E3 ubiquitin ligases of EGFR and establish the inactivation of ZNRF3/RNF43 as a driver of increased EGFR signaling, ultimately promoting cancer progression." (PMID 38260423, 2024). "By identifying ZNRF3/RNF43 as crucial regulators linking EGFR and WNT signaling at the membrane receptor level, our work reveals a novel mechanism of EGFR and WNT coactivation, which is commonly observed in human cancers." (PMID 38260423, 2024). "The most prevalent altered cancer-related genes were CTNNB1 (16%) and ZNRF3 (16%)." (PMID 38023213, 2023). "In this study, the most prevalent altered cancer-related genes were CTNNB1 (16%) and ZNRF3 (16%)." (PMID 38023213, 2023). "ZNRF3/RNF43 loss-mediated EGFR stabilization represents a novel mechanism of EGFR upregulation, explaining the elevated EGFR protein levels observed in many human cancers without EGFR gene amplification or overexpression." (PMID 38260423, 2024). "BRAF mutant cancers did not upregulate RNF43 or ZNRF3 expression at the transcript or protein level, unlike the BRAF wild type cancers that attempt to mitigate the Wnt signal." (PMID 27661107, 2016).
tumor (45 papers, 2014 to 2026). "Here, we aim to fill this knowledge gap by systematically profiling a large number of tumor-associated missense and truncating ZNRF3 variants." (PMID 39674817, 2025). "Here, we extensively studied the functional consequences of truncating and 82 tumor-associated missense ZNRF3 variants." (PMID 39674817, 2025). "For instance, in a mouse model of WNT-dependent CRC with intestine-specific mutations of Rnf43 and Znrf3, a Wnt3 secreting niche provided by Paneth cells was necessary to maintain tumor growth." (PMID 36982422, 2023). "In both the CPCG and TCGA cohorts, patients whose tumor genomes harbored more than one ZNRF3-associated feature were at significantly higher risk of adverse outcomes than those whose genomes harbored one or fewer." (PMID 34716314, 2021). "More recently, the Zinc and ring finger protein 3 (ZNRF3) has been found to be mutated in about 20% of cases and is considered a potential new tumor suppressor gene related to the β-catenin pathway." (PMID 33260476, 2020). "Amongst 16 CTNNB1 wildtype tumours with the presence of nuclear accumulation, five harboured ZNRF3 deletion and one harboured APC mutation." (PMID 29872083, 2018). "To summarize, we extensively analyze tumor-associated ZNRF3 mutations and show that at endogenous levels, all truncating mutations tested exhibit loss-of-function, however, an inverse correlation is observed with longer variants retaining residual functionality." (PMID 39674817, 2025). "Pre-treatment evaluation of ZNRF3 tumor genomic loss and RNA abundance might improve treatment stratification for men with localized prostate cancer." (PMID 34716314, 2021). "Importantly, ZNRF3 loss is associated with higher tumor grade but provides prognostic value independently of grade and other clinical prognostic factors." (PMID 34716314, 2021). "Among these, PTPRK, PTPRM, and PTPRT are implicated as tumor suppressors, raising the possibility that they may also regulate ZNRF3 in certain cell types." (PMID 31934854, 2020). "However, for basically all truncating and missense ZNRF3 variants their functional relevance is currently unknown, meaning that all tumor-associated ZNRF3 mutations are regarded as variants with uncertain significance (VUS)." (PMID 39674817, 2025). "High ZNRF3 expression was present in 46.25% of the cohort and was associated with a small tumor size (average size of 9.7 cm), while low expression was associated with a large tumor size (average size of 13.3 cm) at diagnosis (Z = −2.665; p = 0.008; Mann–Whitney U test)." (PMID 33513905, 2021). "Although ZNRF3 shows little homology with RNF43 in its C-terminal domain, we tested three tumor-associated truncating mutations reported in the equivalent ZNRF3 region (G612tr, G619tr, Q657tr)." (PMID 39674817, 2025). "CRCs with defective ZNRF3 mutations are highly enriched for BRAF-V600E mutation, a mismatch-repair defect, and right-sided tumor location (41/63, 46/56, and 39/47, respectively)." (PMID 39674817, 2025). "In Wnt-dependent cancers characterized by mutations in RNF43/ZNRF3 or by RSPO-fusions, WNTs provided by the tumor cells or the microenvironment are essential for tumor propagation." (PMID 36982422, 2023). "Here, we show that inactivation of Znrf3 in the mouse adrenal cortex, recapitulating the most frequent alteration in ACC patients, is associated with sexually dimorphic tumor progression." (PMID 36240276, 2022). "MGCs were reminiscent of fused macrophages that are observed in granulomatous inflammatory diseases, which suggested a potential involvement of innate immune cells in preventing tumor progression in male Znrf3 cKO adrenals." (PMID 36240276, 2022). "Together, these data strongly suggest that male-specific androgen-driven induction of senescence and SASP results in recruitment, activation, and fusion of highly efficient phagocytes that prevent tumor progression in male Znrf3 cKO mice." (PMID 36240276, 2022).
tumor (continued). "To gain further insight into the potential tumor suppressor function of ZNRF3 in the adrenal cortex, we conducted a kinetic analysis from 4 to 78 weeks." (PMID 36240276, 2022). "The near-universal loss of APC in CRC renders tumours Wnt ligand-independent, bypassing the regulatory activities of RNF43 and ZNRF3." (PMID 36131013, 2022). "Collectively, these data illustrate that ZNRF3*IGF1R PROTABs are tumour-selective for CRC compared with the corresponding normal tissue." (PMID 36131013, 2022). "Here, we show that tumor progression following ablation of Znrf3 within steroidogenic cells of the adrenal cortex is sexually dimorphic." (PMID 36240276, 2022). "Together, these data suggested that ZNRF3 behaved as a classical tumor suppressor in female mice, its ablation resulting in a high frequency of aggressive ACC formation at 78 weeks." (PMID 36240276, 2022). "ZNRF3 expression was negatively correlated with tumor weight (p = 0.026) and tumor size (p = 0.005)." (PMID 33513905, 2021). "ZNRF3 RNA abundance spans a limited range across tumor specimens (mean log2 RNA abundance = 6.63, range: 6.09–7.47)." (PMID 34716314, 2021). "Because deregulation of Wnt/β-catenin pathway promotes tumor formation, RNF43/ZNRF3 can act as tumor suppressors." (PMID 34702444, 2021). "In lung carcinoma, ZNRF3 reduces the expression of Wnt pathway to inhibit the proliferation of tumor cells." (PMID 32612456, 2020). "Given the role of miR-93 as an oncogenesis miR, this miR inhibits ZNRF3 to ensure the viability of tumor cells." (PMID 32612456, 2020). "Median age at operation and tumour size for the group of tumours with APC/CTNNB1/ZNRF3 alterations were 52.5 years and 10 cm respectively and were not significantly different from those without mutations (46 yrs, p = 0.3517, and 10 cm, p = 0.5731)." (PMID 29872083, 2018). "The median overall survival rate for patients with a tumour harbouring APC/CTNNB1/ZNRF3 alteration was significantly lower compared to the ones without (43 vs 114 months, log rank p = 0.0141)." (PMID 29872083, 2018). "Expression levels of ZNRF3 mRNA were significantly higher in tumours harbouring the ∆(2 + 3) deletion (p = 0.0032) and missense mutations (p = 0.0210) in comparison to those without CTNNB1 mutations." (PMID 29872083, 2018). "ChIP qPCR of intestinal epithelial cells established Rnf43 as a direct target of AHR, suggesting that this tumor suppressor, which acts in a complex with ZNRF3, is transcriptionally regulated by AHR." (PMID 30119997, 2018). "In our study, the association was even more evident in the group of patients with tumour harbouring alterations in APC/CTNNB1/ZNRF3." (PMID 29872083, 2018). "Analysis of SNP array data from recurrent tumours available for 4/9 cases with ZNRF3 deletion in the primary tumour showed presence of ZNRF3 deletion in all four recurrent tumours." (PMID 29872083, 2018). "Overexpression of ZNRF3 inhibited cell growth and rescued the tumor-promoting role of miR-146a via inhibition of GSK-3β/β-catenin signaling pathway." (PMID 29088784, 2017). "Further, western blotting analysis showed that knockdown of miR-146a downregulated the expression of ZNRF3 in xenograft tumor tissues." (PMID 29088784, 2017). "Clearly, additional studies are needed to corroborate these findings and to fully understand the function of the R-spondin-ZNRF3/RNF43 signaling module in tumor initiation, maintenance, and metastasis in various tumor types." (PMID 27338477, 2016). "As expected, RNF43 and ZNRF3 mutations tend to be mutually exclusive with APC and β-catenin mutations in those tumor types, reflecting their shared consequences in activating the Wnt/β-catenin signaling pathway." (PMID 27338477, 2016). "Therefore, LGR4/5 and ZNRF3 are required for the suppressive effect of RSPO4 expression on tumor cell migration, invasion and stemness, and RSPO4 exerts these effects through suppressing Wnt signaling." (PMID 41522353, 2026).
tumor (continued). "We found that overexpression of ZNRF3 significantly inhibited tumor growth." (PMID 38260423, 2024). "Interestingly, RSPO2 functions as a tumor suppressor by increasing the accumulation of ZNRF3 and suppressing Wnt signaling." (PMID 38104139, 2023). "We previously showed that conditional ablation of Znrf3 within steroidogenic cells of the adrenal cortex resulted in moderate WNT pathway activation and adrenal zona fasciculata hyperplasia up to 6 weeks, suggesting that ZNRF3 was a potential tumor suppressor in the adrenal cortex." (PMID 36240276, 2022). "Notably, treatment of normal and patient-derived CRC organoids with the ZNRF3*HER2 PROTAB led to tumour-specific degradation, whereas anti-HER2 bivalent antibody resulted in degradation in both normal cells and tumour cells." (PMID 36131013, 2022). "ZNRF3 acts as a tumor suppressor of the Wnt/β-catenin pathway." (PMID 33513905, 2021). "Our results suggest that tyrosine kinases phosphorylating ZNRF3 at its 4Y endocytic signal are candidate targets for Wnt-directed tumor therapy, as their inhibition may promote ZNRF3 internalization and Wnt receptor turnover." (PMID 31934854, 2020). "ZNRF3 has been shown to act as a tumor suppressor, promoting Wnt receptor turnover." (PMID 32287321, 2020). "Significantly lower overall survival rate in patients with tumours harbouring alterations in APC/CTNNB1/ZNRF3 in comparison to those without mutation was observed." (PMID 29872083, 2018). "Homozygous deletions at ZNRF3 locus were observed in 9/52 tumours." (PMID 29872083, 2018). "Our findings of high expression of Cyclin D1 and significantly higher expression of AXIN2, LEF1 and ZNRF3 mRNA in tumours harbouring the ∆(2 + 3) deletion at a similar level to those with hot spot mutations suggest the activating nature of these deleterious mutations in ACCs." (PMID 29872083, 2018). "While the ZNRF3 gene is encoding for an E3 ubiquitin-protein ligase that acts as a negative regulator of the Wnt signaling pathway and a tumor suppressor, no previous report, to our knowledge, exists on the ZNRF3 SNP we identified in the current study." (PMID 25549360, 2014). "Of note, the finding of macrophage infiltration upon Rspo1 overexpression and Znrf3 deletion is contrary to studies in other systems in which WNT/β-catenin activation has been reported to favor exclusion of infiltrating immune cells from the tumor microenvironment." (PMID 37102205, 2023). "Interestingly, for those without WNT mutations, we observed that patients bearing ZNRF3 tumours had a significantly poorer prognosis than patients with WT tumours (p = 0.026)." (PMID 35039505, 2022). "As we could detect no major ZNRF3/RNF43 gene mutations in our patients' tumor, the latter might be functional in our cases." (PMID 29293510, 2018). "This is supported by a recent report that androgen-dependent adrenocortical senescence is induced in Znrf3 conditional knockout mice, a pre-tumour state model of ACC, in which macrophages are recruited to serve as tumour suppressors." (PMID 38570222, 2024). "A ZNRF3*HER2 PROTAB led to significant degradation of HER2 in SW48 cells and in subcutaneously implanted tumours." (PMID 36131013, 2022). "Studies have demonstrated that AHR signalling maintains normal ISC proliferation by promoting Znrf3 and Rnf43 expression to suppress aberrant WNT-β-catenin signalling and tumour progression." (PMID 36555220, 2022). "For instance, in adrenal gland adenocarcinomas, chromothriptic events are predominantly detected on chromosomes 17, 19 and 22, affecting driver genes known to play an essential role in this tumour entity, such as PRKAR1A, MLL4, CCNE1 and ZNRF3, respectively." (PMID 32385320, 2020). "Since R-spondin sensitizes cells to Wnt ligands through inhibiting ZNRF3/RNF43, tumor cells harboring RSPO2/RSPO3 translocations should be sensitive to either direction inhibition of RSPO2/RSPO3 or inhibition of Wnt ligand secretion by porcupine inhibitors." (PMID 27338477, 2016).
tumor (continued). "Lastly, ZNRF3 and HNF6 are EMT and cell-differentiation regulators under normal conditions and are tumor suppressor genes inhibiting the EMT pathway." (PMID 27136531, 2016). "To demonstrate the function of the ZNRF3/RNF43-EGFR signaling pathway in vivo, we first xenografted luciferase-labeled HT29 cells overexpressing either GFP or ZNRF3 into NSG mice by flank injection and monitored tumor growth by bioluminescence imaging." (PMID 38260423, 2024). "Together, these data indicate that loss of ZNRF3 and RNF43 can promote tumor cell growth through EGFR signaling, sometimes even without substantially engaging canonical WNT signaling." (PMID 38260423, 2024). "Therefore, we established intestinal tumor organoids using the intestinal polyps from the Apcmin mice and supplemented RSPO1 in the organoid culture medium to investigate the effect of ZNRF3/RNF43 deactivation on organoid growth and EGFR." (PMID 38260423, 2024). "We could find large numbers of IBA-1+ macrophages (up to 15% of total cells in the tumor) in aggressive tumors in 78-week-old Znrf3 cKO female mice, although they were not differentiated as MERTKhigh active phagocytes." (PMID 36240276, 2022). "Overexpression of ZNRF3 inhibited cell growth and attenuated the tumor-promoting effects of miR-146a via inhibition of GSK-3β/β-catenin signaling, indicating that miR-146a may function as a tumor suppressor and represent a potential biomarker for OS patients." (PMID 29088784, 2017). "However, canonical WNT signaling, based on levels of active-β-Catenin (non-phosphorylated at Ser33/37/Thr41), remained unaffected, suggesting that ZNRF3 suppresses tumor growth through down-regulation of EGRF signaling without substantial involvement of canonical WNT signaling." (PMID 38260423, 2024). "RSPO4 functions as a tumor suppressor by antagonizing canonical and non-canonical Wnt signaling in an LGR4/5- and ZNRF3- dependent manner." (PMID 41522353, 2026). "Exposure to I3C diet for 2 weeks prior to AOM/DSS treatment sufficed to correct the expression of Znrf3 and Rnf43 in an AHR-dependent manner, as mice lacking Ahr in IEC did not upregulate these tumor suppressors." (PMID 30119997, 2018).
ZNRF3 also shares sentences with these, for which no sentence is quoted: colorectal adenocarcinoma (2 papers); esophageal squamous cell carcinoma (2); myopia (2); ovarian carcinoma (2); adrenocortical tumors (1); Arthritis (1); C. perfringens infection (1); campomelic dysplasia (1); colon adenocarcinoma (1); gastric tumor (1); hepatocellular carcinoma (1); hypotrichosis simplex (1); liver fibrosis (1); nephrotic syndrome (1); neuroblastoma (1); neurodevelopmental disorder (1); Obesity (1); pancreatic ductal adenocarcinoma (1); polyposis (1); primary angle-closure glaucoma (1); skin cutaneous melanoma (1); stomach adenocarcinoma (1); type 2 diabetes (1); uterine corpus endometrial carcinoma (1).